BCAM (basal cell adhesion molecule (Lutheran blood group))
Diseases named in the same sentence as BCAM in open-access papers (continued):
Sharing a sentence is not in itself a finding about the gene and the disease.
Brain atrophy (1 paper, 2017). Partial or complete wasting (loss) of brain tissue that was once present. "A polygenic risk score of all rare variants in 3 genes (CBLC, BCAM, RELB) was associated with multifocal brain atrophy, predominantly in the temporal and bilateral frontal lobes." (PMID 28589856, 2017).
cognitive decline (1 paper, 2025). "For example, a study highlights the involvement of APOE and its neighbouring genes (TOMM40, NECTIN2, BCAM) in AD and cognitive decline, partly reinforcing our findings of shared genetic susceptibility between vascular calcification and AD-related traits." (PMID 40149595, 2025).
Congenital dyserythropoietic anemia type IV (1 paper, 2024). Congenital dyserythropoietic anemia type IV (CDA IV) is a newly discovered form of CDA (see this term) characterized by ineffective erythropoiesis and hemolysis that leads to severe anemia at birth. "Genes BCAM linked to congenital dyserythropoietic anemia type IV and PAGE2B associated with recessive X-linked sideroblastic anemia were both up-regulated at R30 compared to baseline." (PMID 38740795, 2024).
glomerulonephritis (1 paper, 2023). A renal disorder characterized by damage in the glomeruli. "BCAM has also been identified as a ligand for integrin α4/β1 on leukocytes in murine glomerulonephritis, but an impact on signal transduction has not been investigated." (PMID 36647260, 2023).
head and neck squamous cell carcinoma (1 paper, 2024). A squamous cell carcinoma that arises from any of the following anatomic sites: lip and oral cavity, nasal cavity, paranasal sinuses, pharynx, larynx, and salivary glands. "Concordantly, we observed a similar pattern of BCAM expression in head and neck squamous cell carcinomas." (PMID 39207605, 2024).
laryngeal carcinoma (1 paper, 2024). Carcinoma that arises from the laryngeal epithelium. "Two cohorts of HNSCC cases (n = 430), YTMA-465 and YTMA-579, including oropharyngeal, hypopharyngeal, and laryngeal carcinoma, were assessed for BCAM expression." (PMID 39207605, 2024).
leukemia (1 paper, 2014). A malignant (clonal) hematologic disorder, involving hematopoietic stem cells and characterized by the presence of primitive or atypical myeloid or lymphoid cells in the bone marrow and the blood. "Apparently a low amount of toxin was taken up into the leukemia cells which do not express Lu/BCAM." (PMID 24453976, 2014).
liver disease (1 paper, 2018). "Here, we show that Lutheran (Lu)/Basal cell adhesion molecule (BCAM) regulates the morphogenesis of DR depending on liver disease models." (PMID 30059007, 2018).
metastatic melanoma (1 paper, 2013). A melanoma that has spread from its primary site to another anatomic site. "BCAM antigen was first identified by monoclonal antibodies raised against human tumor cells, and BCAM has an amino acid sequence with structural homology to MUC18, a human metastatic melanoma cell surface antigen." (PMID 24223164, 2013).
osteosarcoma (1 paper, 2023). A usually aggressive malignant bone-forming mesenchymal neoplasm, predominantly affecting adolescents and young adults. "Furthermore, the function of BCAM may depend on the type of cancer, as ectopic expression of BCAM1 in HT1080 osteosarcoma cells decreased adhesion, while opposite observations were made for motility." (PMID 36647260, 2023).
ovarian tumors (1 paper, 2024). "Expression of BCAM in ovarian tumors had a broad dynamic range with 79.2% of tumors/cases being above the visual threshold (n = 336/424 were BCAM positive)." (PMID 39207605, 2024). "We also examined the PD-L1 expression for 398 ovarian tumors and compared it with BCAM expression." (PMID 39207605, 2024).
tumor (27 papers, 2013 to 2026). "This assumption is supported by the inverse association of BCAM expression with overall survival (OS) reported for different tumour entities." (PMID 36647260, 2023). "This is suggested by the observation that tumour‐associated host cells also express elevated levels of BCAM and/or BCAM‐cleaving proteases." (PMID 36647260, 2023). "Considering the diverse immune infiltration patterns and various expressions of immune evasion biomarkers, such as immune checkpoints, in RCC, it is important to explore the association between BCAM and tumor immune cell infiltration in RCC." (PMID 35941663, 2022). "Data from the Clinical Proteomic Tumor Analysis Consortium further validated the association between low BCAM expression and CD8 + inflamed phenotype at protein level." (PMID 35941663, 2022). "We also analyzed the correlation between BCAM gene expression and tumor mutation burden (TMB)/microsatellite instability (MSI)." (PMID 35941663, 2022). "Lu/BCAM (Lutheran/basal cell-adhesion molecule, a glycoprotein) belongs to the immunoglobulin superfamily which contains both Lu blood group and BCAM tumor-associated antigens." (PMID 28841878, 2017). "Previous studies identified that the dysfunction of BCAM might be involved in cell adhesion, migration and tumor metastasis, which might explain the association of adverse clinicopathological parameters and poor prognosis with low expression of BCAM in ccRCC." (PMID 35941663, 2022). "Similarly, high Lu/BCAM expression was detected in the tumors of human renal pelvis, ureter and bladder, and was significantly associated with advanced tumor stage (p = 0.02)." (PMID 28841878, 2017). "Finally, we addressed the question whether BCAM/MMT cluster genes associated with poor survival in OC might also have clinical relevance in other tumor types." (PMID 40082910, 2025). "The level of VEGFA, which is induced 177-fold in CM from BCAM-overexpressing (BCAM-OE) tumor cells, showed a significant correlation with the concentration of soluble BCAM (Pearson r = 0.51; p = 5.6 × 10− 6)." (PMID 40082910, 2025). "This increased motility unexpectedly manifested as mesothelial cell migration away from the spheroid attachment site, suggesting a repulsive effect of BCAM-expressing tumor cells on mesothelial cells." (PMID 40082910, 2025). "This was further validated in a mouse model of peritoneal dissemination for BCAM-OE cells, where a dramatic BCAM-dependent increase in tumor blood vessel formation was observed." (PMID 40082910, 2025). "Conversely, a striking stimulatory effect on tumor blood vessel growth was observed in mice injected with either BCAM-OE clone." (PMID 40082910, 2025). "BCAM influences tumor cell adhesion and migration; however, in OC its effect appears to be inhibitory, suggesting a potential tumor-suppressive role." (PMID 40082910, 2025). "Consistent with the secretome data, BCAM induced endothelial tube formation in vitro and markedly promoted tumor angiogenesis in a mouse model." (PMID 40082910, 2025). "BCAM competes with integrins and through the preferential binding of BCAM to laminin, tumor cell migration is promoted." (PMID 39207605, 2024). "A broad range of BCAM protein expression measured by signal/staining intensity in QIF was seen across multiple tumor types in YTMA-395 (multi-tumor array)." (PMID 39207605, 2024). "Based on this observation, we further explored the staining pattern of BCAM in these specific tumor types in larger tumor population for each type." (PMID 39207605, 2024). "The BCAM-laminin interaction activates signaling pathways that promote tumor cell motility and invasion, highlighting BCAM's potential involvement in tumor progression." (PMID 39207605, 2024). "Research has demonstrated that in tumor cells, Lu/BCAM competes with integrin α3β1 to bind to LM-511, resulting in weakened intercellular adhesion and an enhanced tumor cell migration ability." (PMID 39000374, 2024).
tumor (continued). "Soluble BCAM (as recombinant Fc‐BCAM) affects tumour cells in culture at a concentration corresponding to the highest sBCAM levels in ascites, strongly supporting a role in the OC TME." (PMID 36647260, 2023). "The inhibitory effects of BCAM on known functions of tumour cells, that is, adherence and migration of single cells, cannot explain its association with a poor clinical outcome." (PMID 36647260, 2023). "BCAM reduces compaction of tumour cell spheroids, thereby facilitating their invasion of metastatic sites." (PMID 36647260, 2023). "This is in perfect agreement with our finding that tumour‐cell‐mediated clearance of a mesothelial cell monolayer is promoted by BCAM." (PMID 36647260, 2023). "While BCAM appears to have tumour‐suppressive effects on single cells, it promotes the dispersion of OC cell spheroids by regulating LAMA5‐integrin‐β1‐dependent compaction and thereby facilitating invasion of metastatic target sites." (PMID 36647260, 2023). "The results revealed that BCAM mRNA expression negatively correlated with age, pT stage, metastatic status and tumor grade (all p < 0.05)." (PMID 35941663, 2022). "For ccRCC, the expression of BCAM was again inversely correlated with pT stage, metastatic status and tumor grade." (PMID 35941663, 2022). "Firstly, we evaluated the differential expression of BCAM in tumor and normal tissues at pan-cancer RNA level from TCGA (The Cancer Genome Atlas) database." (PMID 35941663, 2022). "After that, we analyzed data from the CPTAC database and found that the relationship between BCAM expression at the protein level and tumor grading was consistent with that at the mRNA level." (PMID 35941663, 2022). "The tumorigenicity of Lu/BCAM was demonstrated by focus formation, colony-forming ability, tumour formation, cell adhesion and migration." (PMID 28841878, 2017). "In order to analyze the function of BCAM protein in tumor cell growth, we introduced a BCAM cDNA expression vector into K2 cells." (PMID 24223164, 2013). "Though more study is needed, our results indicate phosphorylation of the BCAM cytoplasmic domain plays an important role in tumor suppression." (PMID 24223164, 2013). "Nevertheless, in the same study, we uncovered novel functions of BCAM in OC that may contribute to metastasis by promoting the trans-mesothelial invasion of tumor cells into peritoneal organs, particularly the omentum." (PMID 40082910, 2025). "The impact of BCAM on the tumor cell secretome and the mesothelial cell phenotype was analyzed by affinity proteomics, bulk and single-cell RNA sequencing, life-cell and multiphoton microscopy, biochemical and functional in vitro assays as well as a murine tumor model." (PMID 40082910, 2025). "Notably, several of these factors are also present in the BCAM-induced tumor cell secretome, suggesting that BCAM initiates a pro-tumorigenic mechanism in tumor cells that is amplified by mesothelial cells." (PMID 40082910, 2025). "Additionally, this distinctive expression profile underscores the importance of further investigating BCAM’s role in tumor biology." (PMID 39207605, 2024). "Moreover, BCAM plays a crucial role in promoting the invasion of metastatic sites by reducing the compaction of tumor cell spheroids." (PMID 39000374, 2024). "This contradiction highlights the context-dependent nature of BCAM’s prognostic significance, which may differ based on tumor microenvironment or therapy responsiveness." (PMID 39207605, 2024). "Mechanistically, BCAM contributes to carcinogenesis by promoting cancer cell adhesion to basement membranes, cell chemotaxis, and tumor cell migration through the disruption of normal cell–cell and cell–matrix interactions; it is thus related to the invasion and metastasis of tumor cells." (PMID 39207605, 2024). "The BCMA–CST6–CAR-T and BCAM–CAR-T cells had very similar tumor growth–inhibiting effects." (PMID 37883186, 2024).
tumor (continued). "After antibody validation, we performed the screening of BCAM expression in several tumor types." (PMID 39207605, 2024). "Importantly, BCAM1‐overexpressing OVCAR8‐OE cells invaded not only milky spots but also areas distant to milky spots, which is consistent with the observed BCAM‐dependent clearance of a mesothelial cell monolayer by tumour cells in vitro." (PMID 36647260, 2023). "Importantly, BCAM was recently identified as target of miR-199a-5p in skin keratinocytes, where it acts as a tumor suppressor by inhibiting invasiveness, and in placenta, where it inhibits trophoblast proliferation, migration and invasion." (PMID 37700183, 2023). "Literature reports on the role of BCAM in cancer progression do not provide a consistent picture describing both tumour‐promoting and suppressive functions and clinical associations (see Background)." (PMID 36647260, 2023). "Finally, we utilized CPTAC (Clinical Proteomic Tumor Analysis Consortium) database to reconfirm the expression difference of BCAM between tumor and normal tissues in ccRCC at the protein level." (PMID 35941663, 2022). "Non-PTS KRT14+ epithelial/tumor cells uniquely expressed known BCC-associated gene biomarkers including BCAM and EPCAM." (PMID 35687691, 2022). "BCAM's role as a laminin receptor is presumed to play a potential role in malignant and metastatic tumors because of evidence suggesting that laminin interacts with tumor cells to promote malignant and metastatic phenotypes." (PMID 24223164, 2013). "In fact, there are reports that BCAM affects tumor development." (PMID 24223164, 2013). "Moreover, its significant role in tumor cell proliferation and invasion suggests that inhibiting BCAM may impair cancer progression and metastasis, establishing it as a promising candidate for targeted therapy." (PMID 39207605, 2024). "Likewise, the role of BCAM in tumour cell spheroids despite their crucial role in OC metastasis remains unknown." (PMID 36647260, 2023). "Therefore, to investigate whether the cytoplasmic domain of BCAM is essential for tumor suppression, we established a BCAM cytoplasmic domain deletion mutant (Δ571– 624) expression vector and introduced it into K2 cells." (PMID 24223164, 2013). "Given the observed induction of endothelial tube formation by CM from BCAM-stimulated cells, we investigated the role of BCAM expression in OVCAR-8 cells on tumor blood vessel formation in a mouse model of peritoneal OC dissemination." (PMID 40082910, 2025). "Among these, KRT14+ epithelial/tumor cells derived from tumor tissue significantly expressed unique BCC-related gene molecular markers, such as BCAM and EPCAM." (PMID 41383502, 2025). "The upregulations of S100A4, MARCKSL1, BCAM, BAG4, IPO4 and CPSF7 in pHAGE-ELL(C595A) tumours were confirmed." (PMID 27009366, 2016). "While BCAM’s impact on MMT may facilitate initiation of micrometastases, neo-angiogenesis is essential for tumor growth." (PMID 40082910, 2025). "In thyroid cancer tumor tissue, Lu/BCAM expression is downregulated compared to normal thyroid tissue, and its expression is negatively correlated with tumor size and lymph node metastasis." (PMID 39000374, 2024). "The widespread expression of BCAM across multiple tumor types, coupled with its lack of correlation with PD-L1 expression, highlights its potential as a predictive novel biomarker across various cancer types." (PMID 39207605, 2024). "Taken together, these observations strongly suggest that BCAM‐mediated dispersion of spheroids promotes trans‐mesothelial invasion, probably due to weakening of integrin‐β1‐LAMA5‐mediated intraspheroidal cohesion of tumour cells." (PMID 36647260, 2023). "Other targets of miR-199a that may affect tumor proliferation and metastasis are ROCK1, HIF1α, BCAM, FZD6, and DDR1." (PMID 36499729, 2022).
tumor (continued). "As a member of the immunoglobulin superfamily, CD146 displays many similarities in the structure with BCAM (B-cell adhesion molecule) and ALCAM (activated leukocyte cell adhesion molecule), but also many similarities in functions and expression in tumor and endothelial cells." (PMID 31548532, 2017). "The secreted factors induced by BCAM in tumor cells, and indirectly through the tumor cell secretome in mesothelial cells, likely cooperate to promote angiogenesis, e.g. through VEGFB produced by tumor cells, CXCXL8 expressed by mesothelial cells and FGF2 secreted by both cell types." (PMID 40082910, 2025). "In tumour cells, BCAM‐mediated signal transduction has not been investigated to date." (PMID 36647260, 2023). "In view of the known pivotal role of spheroids rather than single tumour cells in transcoelomic spreading and the observed deposition of LAMA5‐containing laminin in spheroids, we investigated a potential function of BCAM as a laminin‐interacting protein in spheroid formation and dynamics." (PMID 36647260, 2023).